COQ2 (coenzyme Q2, polyprenyltransferase)
Diseases named in the same sentence as COQ2 in open-access papers (continued):
Sharing a sentence is not in itself a finding about the gene and the disease.
retinitis pigmentosa (1 paper, 2020). Retinitis pigmentosa (RP) is an inherited retinal dystrophy leading to progressive loss of the photoreceptors and retinal pigment epithelium and resulting in blindness usually after several decades. "Interestingly, COQ2 is the only gene in the CoQ10 biosynthesis pathway that has been definitively linked with a retinitis pigmentosa-like presentation in the reported literature." (PMID 33187544, 2020). "In previously reported patients with retinitis pigmentosa stemming from variants in the COQ2 gene, treatment with CoQ10 supplementation was not administered." (PMID 33187544, 2020).
steroid-resistant nephrotic syndrome (1 paper, 2018). Nephrotic syndrome, occurring in the pediatric population, in which proteinuria does not normalize with administration of steroids; this condition is unresponsive to a minimum of four weeks administration of oral corticosteroids. "Among the so far studied genes, 4: PDSS2/COQ1, COQ2, COQ6, and ADCK4/COQ8B are associated with steroid-resistant nephrotic syndrome (SRNS)—they are mutated in about 1% of cases." (PMID 30232548, 2018).
Stroke (1 paper, 2023). Sudden impairment of blood flow to a part of the brain due to occlusion or rupture of an artery to the brain. "Stroke-like episodes were reported as a potential disease feature of several CoQ10 biosynthesis defects (COQ2, COQ4 and COQ8A)." (PMID 36978966, 2023).
synucleinopathy (1 paper, 2015). A neurodegenerative disease that is characterized by the abnormal accumulation of aggregates of alpha-synuclein protein in neurons, nerve fibers or glial cells. "Given the fact that these disorders share some common pathological changes such as the Lewy body formation and synucleinopathy, we hypothesize that COQ2 mutation may also be involved in the pathogenesis of these diseases." (PMID 25977831, 2015).
myopathy (3 papers, 2007 to 2023). A disease of the muscle in which the muscle fibers do not function properly. "It has been validated that polymorphisms in the SLCO1B1 gene, which encodes the protein responsible for hepatic uptake of statins, and the COQ2 gene, which encodes an enzyme involved in the synthesis of coenzyme Q10, are strongly associated with statin-induced myopathy." (PMID 37849732, 2023). "Because mutations in the COQ2 gene are associated with severe inherited myopathy, we hypothesized that common, mild genetic variation in COQ2 would be associated with inter-individual variation in statin intolerance." (PMID 17376224, 2007).
mitochondrial disease (2 papers, 2019 to 2024). "In rare cases, specific therapies may exist for mitochondrial diseases caused by single-gene pathogenic variants such as COQ2, COQ6, or COQ8b." (PMID 38877226, 2024).
tumor (2 papers, 2023 to 2025). "The expression of the three genes, COQ2, MPC1, and ADAMTS13, in normal and tumor tissues was analyzed, revealing that the expression of MPC1 was higher in normal tissues, while ADAMTS13 was higher in tumor tissues." (PMID 37691826, 2023).
cancer (1 paper, 2022). A tumor composed of atypical neoplastic, often pleomorphic cells that invade other tissues. "Regrettably, cancer-related studies of the other few candidate genes, including BCS1L, COQ2, and SLC39A8, are still absent, and we will seriously consider deeper research in our future studies." (PMID 36185199, 2022).
cardiovascular disease (1 paper, 2022). "Since the CM promoter interaction map linked SNPs to target genes relevant with cardiovascular disease, LIN54, COQ2, and FAM175A were prioritized for further TF correlation analysis." (PMID 36568976, 2022).
retinopathy (1 paper, 2020). "Thus, CoQ10 supplementation in patients with retinopathy should be considered as a possible treatment to stabilize remaining retinal function in individuals with the ocular complications associated with pathogenic COQ2 variants." (PMID 33187544, 2020).
COQ2 also shares sentences with these, for which no sentence is quoted: Encephalopathy (5 papers); hypertrophic cardiomyopathy (4); Ataxia (2); co-infection (2); Leigh syndrome (2); malaria (2); Progressive encephalopathy (2); amyotrophic lateral sclerosis (1); cardiomyopathy (1); cerebellar degeneration (1); cognitive decline (1); Dent disease (1); developmental delay (1); Duchenne muscular dystrophy (1); end-stage renal disease (1); essential tremor (1); Fabry disease (1); Failure to thrive (1); Friedreich ataxia (1); glycogen storage diseases (1); hereditary nephrotic syndrome (1); hereditary optic neuropathy (1); hypopharyngeal cancer (1); infection (1); Intellectual disability (1); Lewy body disease (1); Lowe syndrome (1); MELAS (1); Methylmalonic aciduria (1); Middle East respiratory syndrome (1).
A further 9 diseases each share a sentence with COQ2 in 1 paper.